IFITM3 (interferon induced transmembrane protein 3)
Diseases named in the same sentence as IFITM3 in open-access papers (continued):
Sharing a sentence is not in itself a finding about the gene and the disease.
COVID-19 (continued). "Thus, genetic variants influencing the function of TMPRSS2 and IFITM3 may be expected to contribute to the expression of severe symptoms of COVID-19, or may convey the protective effect." (PMID 35949487, 2022). "A significant correlation was observed between the mortality rate with COVID-19 for ethnic groups in Britain and the combined frequency of IFITM3 alleles rs12252 and rs34481144 in these ethnic groups, suggesting that these alleles may be associated with more severe outcomes." (PMID 34434219, 2021). "The higher frequency of the IFITM3-rs-12252 allele among African Americans (0.15–030) compared to Caucasians (0.01–0.05) may also be an important factor in the higher severity and death rate seen with COVID-19 in African Americans." (PMID 34434219, 2021). "Τhis was a finding from a single case report; however, as the prevalence of this SNP is 26.5% in the Chinese population (the 1000 Genomes Project), further investigation of the IFITM3-rs12252-C/C allele in larger cohorts of people with COVID-19 may be worth pursuing." (PMID 33092637, 2020). "This study further elucidates the role of IFITM3 in viral entry and highlights the potential dangers of treating COVID-19 patients, with invasive pulmonary mucormycosis, using AmB." (PMID 40464579, 2025). "DEG analysis revealed a common inflammatory phenotype across both HIV-1 and COVID-19 which included known IFN-I signaling genes such as IFITM3 and IFI27." (PMID 36992700, 2023). "Patients with IFITM3 rs34481144 CT genotypes had significantly higher COVID-19 mortality compared to patients with other genotypes; however, COVID-19-recovered patients had CC genotypes." (PMID 37323564, 2023). "Recent research has associated the interferon-induced transmembrane protein 3 gene (IFITM3) with the outcomes of coronavirus disease 2019 (COVID-19), although the findings are contradictory." (PMID 37323564, 2023). "IFITM-3 AG + GG, ACE-2 CT + TT variants, and IL-6 were found to be significant predictors for COVID-19 severity (p < 0.001) in a univariate logistic regression analysis." (PMID 38155729, 2023). "We investigated the relationship between COVID-19 progression and genetic variants in both ACE-2 and IFITM-3." (PMID 38155729, 2023). "Both ACE-2 and IFITM-3 SNPs were amongst the highest determinants of COVID-19 severity, together with IL-6, CRP, D-dimer, ferritin, preexisting comorbidities, and age." (PMID 38155729, 2023). "For instance, a meta-analysis conducted by Li and colleagues assessed the association between interferon-induced transmembrane protein 3 (IFITM3) variants and susceptibility to COVID-19." (PMID 37630479, 2023). "Recently published systematic review and meta-analysis on the relation between ACE1, ACE2, TMPRSS2, IFITM3, and VDR genes polymorphisms and COVID-19 outcomes has elucidated the potential involvement of these SNPs in COVID-19 outcomes." (PMID 36743382, 2023). "Several studies have identified numerous genetic variants correlated with COVID-19 severity, including ACE2, ABO, CD26, IFITM3, HLA, TLR7, and TMPRSS2." (PMID 38138892, 2023). "The recent outbreak of COVID-19 by SARS CoV2 led to studies on the relation between IFITM3 and COVID-19 infection." (PMID 36153346, 2022). "rs12252, related to the IFITM3 gene, shows some relevance with the Han Chinese population’s COVID-19 severity." (PMID 35022007, 2022). "The main objective of the present study is to elucidate effects of naturally occurring variants within ACE1, ACE2, TMPRSS2, IFITM3 and VDR genes on clinical severity of COVID-19 and/or the outcome of SARS-CoV-2 infection." (PMID 35949487, 2022). "Previous work has shown increased expression of IFITM3 in platelets from COVID-19 patients; our dataset includes the differential abundance of ISG15 and IFITM1, reinforcing the importance of platelets in antiviral response." (PMID 35842415, 2022).
COVID-19 (continued). "This analysis revealed a positive correlation between the levels of expression of IFITM1 and IFITM3, even when their overall expression patterns looked contrasting when compared with HC and COVID-19 patients." (PMID 35708622, 2022). "In the studies, after classifying the patients according to their degree of the disease, rs12252 in the IFITM3 gene was commonly observed in severe COVID-19 patients." (PMID 35022007, 2022). "Here, we present the result of a systematic review and, whenever possible, a meta-analysis of IFITM3, FURIN, ACE1, and TNF-α genetic association with susceptibility to SARS-CoV-2 infection and COVID-19 severity." (PMID 35432458, 2022). "IFITM3 expression was found to be higher in the nasopharyngeal swabs of COVID-19 patients and the expression of IFITM3 increased with infection time of COVID-1929." (PMID 36153346, 2022). "The pattern of IFITM3 gene expression in PBCs was similarly affected by COVID-19 and COVID-19 severity in both sexes, yet only male obese patients displayed a greater expression than overweight patients (one-way ANOVA, post-hoc analysis)." (PMID 36009555, 2022). "Genotyping of rs12252 (42 T/C) SNP of the IFITM3 gene showed that TT genotype was more prevalent among a moderate patient group where CC genotype was found to be more frequent in critically ill COVID-19 patients." (PMID 35822078, 2022). "In COVID-19, the IFITM3 gene was recently found to be upregulated in platelets and epithelial cells." (PMID 35842415, 2022). "In fact, similar to that of ADAM17 mRNA levels, the increase in IFITM3 mRNA levels found in PBCs of COVID-19 patients was greater the higher the severity observed in the ultimate course of the disease, and maximal in patients with obesity (BMI > 30)." (PMID 36009555, 2022). "Based on the important risk factors for COVID-19 severity, we evaluated the effects of IFITM3 rs6598045, SARS-CoV-2 variants, and quantitative polymerase chain reaction (qPCR) cycle threshold (Ct) values on COVID-19 mortality." (PMID 36403064, 2022). "Genotype distribution for rs12252 (42 T/C) SNP of the IFITM3 gene between the different groups of COVID-19 patients and healthy controls showed that CC genotype was statistically associated with disease severity (p < 0.001)." (PMID 35822078, 2022). "We suggest that the increased expression of both ADAM17 and IFITM3 plays an important role in the boosted pathogenesis of COVID-19 in male patients with obesity." (PMID 36009555, 2022). "We and others reported that many IFN-inducible genes, including IFITM3, were upregulated in COVID-19 patients." (PMID 36423162, 2022). "In this study, genotype of rs12252 (42 T/C) SNP of the IFITM3 gene showed that the TT genotype was more prevalent among moderate (78.6%) COVID-19 patients, whereas CC genotype was more common in critically ill (50%) patients." (PMID 35822078, 2022). "Patients with the IFITM3 rs6598045 GG and AG genotypes showed a considerably greater COVID-19 death rate compared to patients with other genotypes." (PMID 36403064, 2022). "To investigate the possible association of these SNPs with SARS-CoV-2 infection, we sequenced the IFITM3 locus of 203 hospitalized COVID-19 patients, which included 133 mild cases (65.5%), 43 severe cases (21.2%), and 27 deaths (13.3%)." (PMID 36423162, 2022). "We further observed the association of the rs12252 SNP in IFITM3 with a higher risk of SARS-CoV-2 acquisition, thus revealing one genetic factor underpinning the susceptibility to COVID-19." (PMID 36423162, 2022). "A list of previously reported associated variants was confirmed and two variants in the enhancers of IFITM3 genes that might affect disease severity by regulating the gene expression were newly identified, which will lead to a better understanding of the host genetic factors at play in COVID-19." (PMID 36531218, 2022).
COVID-19 (continued). "Accordingly, MKs undergoing shortened differentiation and expressing anti-viral IFITM1 and IFITM3 RNA as a sign of viral sensing were enriched in the circulation of deadly COVID-19." (PMID 35708858, 2022). "Gene expression levels of ADAM17 and IFITM3 were increased in PBCs of COVID-19 patients compared with control subjects (by 63% and 700%, respectively)." (PMID 36009555, 2022). "The inflammatory mediator of EN-RAGE encoded by S100A12 was significantly correlated with COVID-19, and S100A8, S100A9, IRF3, IFI6, IFITM1, and IFITM3 have been reported to elicit autoinflammatory and autoimmune conditions in response to SARS-CoV-2 infection." (PMID 35172892, 2022). "The relationship between the COVID-19 mortality rate with IFITM3 rs6598045 and qPCR Ct values was investigated in three variants but not in other variants due to the non-availability of data." (PMID 36403064, 2022). "While the expression of IFITM1 and IFITM3 was prominent in the villous core and perivascular regions, IFITM3 was also localized to trophoblasts, and was upregulated in women with severe COVID-19." (PMID 34257394, 2021). "Many of the genes previously identified as increased within all cells from COVID-19 participants, e.g., anti-viral factors IFITM3, MX1, IFI44L, and IRF1, are upregulated among SARS-CoV-2 RNA+ cells compared to matched bystanders." (PMID 34352228, 2021). "We also showed that IFITM3 protein expression, which localized to early and late endosomes, was enhanced in severe COVID-19." (PMID 34257394, 2021). "We found that placental mRNA expression of IFITM1 and IFITM3 was upregulated in participants with severe disease when compared to asymptomatic/mild COVID-19-positive pregnant women." (PMID 34257394, 2021). "Lung and circulating immune cells were reported to express less IFITM3 than other tissues, and this was a suggestive reason for COVID-19 severity and cytokine release syndrome." (PMID 32595654, 2020). "In conclusion, we obtained the worldwide case fatality rates of COVID-19 and genetic information on the IFITM3, ACE2, TMPRSS2, and IL6 genes." (PMID 33396837, 2020). "This study calls for further focus on the role of IFITM3 variants in the mechanism of cellular invasion of SARS-CoV-2, their impact in COVID-19 severity and their possible implications in vaccination efficacy." (PMID 33240681, 2020). "IFITM3 variants have not shown any contribution to COVID-19 in European, Middle Eastern, and Asian populations." (PMID 40296872, 2025). "In addition, RSAD2 and IFITM3 were among the consensus up-regulated genes in our previous meta-analysis of COVID-19 transcriptome datasets." (PMID 40872774, 2025). "To do so, we aimed to identify significantly enriched IFN-I signatures and genes along the transolfactory route employing published datasets of the nasal mucosa and olfactory bulb amygdala transcriptomes of COVID-19 patients and determine the presence of IFITM3 specifically in those gene networks." (PMID 38785545, 2024). "Dysregulated IFITM3 networks in brain endothelial cells in the setting of COVID-19 have been previously identified, providing further support to our hypothesis of an outside-in quasinfectious transmission of this dysregulation to the CNS." (PMID 38785545, 2024). "Furthermore, several studies, including those from our group have outlined IFITM3 pathways as overlapping networks between Alzheimer’s disease and COVID-19." (PMID 38785545, 2024). "Another study found that a higher prevalence of IFITM3 rs34481144 T allele carriers was not seen in “severe” COVID-19 patients." (PMID 37323564, 2023). "With regard to vaccination against COVID-19, the impact of these SNPs in the gene IFITM3 on the humoral immune response following immunization remains unknown." (PMID 37515072, 2023). "High expression of IFITM2 and IFITM3 has been widely detected in individuals with COVID-19." (PMID 38077419, 2023).
COVID-19 (continued). "In this study, we investigated for the first time whether rs12252 and rs34481144 in the IFITM3 gene influence the humoral immune response after vaccination against COVID-19 with mRNA vaccines." (PMID 37515072, 2023). "The identified genotypes and their alleles were significantly correlated with COVID-19 clinical deterioration as follows: ACE2 rs2285666 CT + TT, odds ratio (95% confidence interval): 12.136 (2.784–52.896) and IFITM-3 rs12252 AG + GG: 17.276 (3.673–81.249), both p < 0.001." (PMID 38155729, 2023). "Additionally, IL1B and IFITM3 were found to be upregulated in these cells in patients with severe COVID-19, when compared to healthy or asymptomatic individuals or patients with mild disease." (PMID 37795240, 2023). "The COVID-19 mortality rate was related to mean age, ALT, HDL, LDL, FBS, uric acid, creatinine, ESR, 25-hydroxyvitamin D, real-time PCR Ct values, SARS-CoV-2 variants, and IFITM3 rs6598045 GG." (PMID 36403064, 2022). "Therefore, we focused our systematic review on IFITM3, FURIN, ACE1, and TNF-α genetic variants and their association with COVID-19 susceptibility and prognosis to reduce unnecessary duplication." (PMID 35432458, 2022). "From our results, it is worth highlighting the large increase (7-fold) in the expression of the gene encoding the interferon-induced transmembrane (IFITM) protein 3 (IFITM3) in PBCs of patients with COVID-19, a gene upregulated soon after the infection of lung epithelial cells by SARS-CoV-2." (PMID 36009555, 2022). "Conversely, both pandemic influenza A(H1N1) and COVID-19 showed a modest, but significant upregulation of IFITM3 compared to HC, which might reflect the higher circulation of monocytes and neutrophils during these infections." (PMID 35708622, 2022). "In this context, only a few studies have found a correlation between the prevalence of SNPs affecting IFITM3 and susceptibility to COVID-19 without influencing disease severity and mortality (Gómez and others 2021; Schönfelder and others 2021)." (PMID 35708622, 2022). "Using comparative groups of healthy controls (HC) and individuals with coronavirus disease 2019 (COVID-19), we found that low IFITM1 and increased IFITM3 leukocyte expression are distinctive features of pandemic influenza A(H1N1)." (PMID 35708622, 2022). "Therefore, our primary aim was to investigate the association between found SNPs, IL-6 (rs1800796), IL-10 (rs1800896), TNF-α (rs1800629), and IFITM3 (rs12252) and the presence of post-COVID pain in individuals previously hospitalized by COVID-19." (PMID 36233516, 2022). "Moreover, studies are still required to adequately evaluate IFITM3, FURIN, and TNF-α genetic variants’ role in COVID-19 susceptibility and outcomes." (PMID 35432458, 2022). "However, IFITM3 rs6598045 appears to play a more dominant role in COVID-19 severity than the other two SNPs." (PMID 36403064, 2022). "In this study, we evaluated the expression of IFITM1 and IFITM3 in peripheral leukocytes from healthy controls and individuals with severe pandemic influenza A(H1N1) or coronavirus disease 2019 (COVID-19)." (PMID 35708622, 2022). "In the Bangladeshi population, there is no data regarding the association of IFITM3 gene polymorphism and disease progression in COVID-19 patients." (PMID 35822078, 2022). "In addition, the rs12252 single nucleotide polymorphism (SNP) of the interferon-induced transmembrane protein 3 (IFITM3) gene is related to the severity of COVID-19 in the Han Chinese population." (PMID 33396837, 2020). "However, taken together, this set of results constitutes a clear and valid starting point for designing further investigations regarding the role of IFITM3 in COVID-19 severity and appears as one more piece of evidence towards this direction." (PMID 33240681, 2020).
COVID-19 (continued). "Indeed, the accumulation of many direct and indirect layers of evidence linking IFITM3 with COVID-19 severity, has also led to explicit calls for further investigation of the role of this highly relevant first-line of cellular defense protein." (PMID 33240681, 2020). "Notably, only the MAF of the rs6598045 SNP of the IFITM3 gene showed a strong correlation (r2 = 0.8901, p = 0.0047) with the case fatality rate of COVID-19." (PMID 33396837, 2020). "During this time, we observed the kinetics of the humoral immune response after basic immunization as well as after the first booster vaccination and investigated whether SNPs in the IFITM3 gene influence the humoral immune response after vaccination against COVID-19 with mRNA vaccines." (PMID 37515072, 2023). "Evaluating the serum levels of IP-10, MCP-1, MIP-1α, and IL-6 and genotyping of rs12252 SNP of IFITM3 gene among different categories of COVID-19 patients might aid in understanding the pathogenesis of COVID-19 and contribute to developing disease-specific biomarkers and therapeutic strategies." (PMID 35822078, 2022). "It was previously shown that IFITM3 facilitates replication of the seasonal coronavirus hCoV-OC43, while we and others recently showed that SARS-CoV-1 and SARS-CoV-2 infection is inhibited by ectopic and endogenous IFITM1, IFITM2, and IFITM3 from mice and humans." (PMID 33880473, 2022). "Also, patients recovering from COVID-19 had the IFITM3 rs6598045 AA genotype." (PMID 36403064, 2022). "Finally, suppression of the viral response genes (MX1 (p < 0.05), SAMHD1 (p < 0.001), IFITM3 (ns)) occurred more in severe ventilation-associated COVID-19 cases compared to non-ventilated cases." (PMID 33633121, 2021). "Further potential involvement of IFITM3 in COVID-19 outcome was revealed in the context of syncytial pneumocytes in severe cases with extensive lung damage, where it was suggested that the cellular location of IFITMs 1–3 could be playing a role in syncytia formation." (PMID 33240681, 2020). "If functional differences between the examined IFITM3 haplotypes are shown to produce distinct profiles of COVID-19 progression in severe patients, then an improved understanding of the underlying mechanisms may allow more adequate or personalized treatment protocols." (PMID 33240681, 2020). "Notably, the anti-virus protein IFITM3 also expressed much lower in lung than other tissues, which might be related to the severe lung symptoms of COVID-19." (PMID 33061814, 2020). "However, the purpose of the pooled analysis was mainly to reinforce the primary association between IFITM3 and COVID-19 severity rather than to (indirectly) infer causality." (PMID 33240681, 2020). "One example is the expansion of platelets in severe COVID-19 samples, comprising CRBN/RBX1-high (M33) and IFITM3-high (M34) subpopulations." (PMID 41066207, 2025). "Conversely, in silico perturbation of COVID-19 human blood cells using human-Geneformer model predicted that deletion of genes CXCL2, IFITM3, and CCL20 would revert the COVID-19 cells towards a normal state." (PMID 40106407, 2025). "One example is the expansion of platelets in severe COVID-19 samples, comprised of CRBN/RBX1-high (M33) and IFITM3-high (M34) subpopulations." (PMID 39764102, 2024). "Using this approach, genes S100A8, IFI27, CLU, IFITM3, and MT-CO1 have been identified as the stable gene panel for the classification of severe COVID-19 patients, utilizing the same training dataset as previously employed." (PMID 39350339, 2024). "This work was performed to identify possible COVID-19 prognostic markers with special concern for ACE-2 and IFITM-3 genetic variations and IL-6 level assays." (PMID 38155729, 2023). "A reduced abundance of naïve CD8 T cells with decreased expression of antiviral defense genes (i.e., IFITM3 and TRIM22) was identified in aged patients with severe COVID-19." (PMID 37199576, 2023).